CCNYL1B (cyclin Y like 1B)
Gene: Protein-coding gene on chromosome 16 (34,351,499 to 34,381,110, reverse strand). Ensembl gene ENSG00000284209.
Gene Ontology:
Molecular function: cyclin-dependent protein serine/threonine kinase activator activity
Biological process: regulation of canonical Wnt signaling pathway
Cellular component: plasma membrane
Homologues: Orthologues: macaque CCNYL1B (87% identical), tropical clawed frog ccnyl1 (57% identical), zebrafish ccnyl1 (53% identical), Drosophila melanogaster CycY (46% identical), Caenorhabditis elegans cyy-1 (42% identical). Paralogues in human: CCNYL1 (59% identical), CCNY (52% identical).